TNF (tumor necrosis factor)
Diseases named in the same sentence as TNF in open-access papers (continued):
Sharing a sentence is not in itself a finding about the gene and the disease.
depression (continued). "Our findings indicate that acupuncture can reduce TNF-α and IL-1β levels while increasing IL-10 and IL-4 levels in depression animals." (PMID 41244868, 2025). "In animal models of depression, early-life stress significantly increased the expression levels of IL-1β, IL-6, and TNF-α in the brain, while blood levels remained unchanged." (PMID 41301474, 2025). "In a fully adjusted model, depression was significantly associated with higher levels of IFN-γ and IL-1ra; IL-33, CCL-2, CCL-4 and TNF- α remained significant below the Bonferroni threshold." (PMID 39922907, 2025). "We noticed that in the group suffering from depression, there were also positive correlations between IL-8 and SD and also between TNF-alpha and self-directedness (SD)." (PMID 40002454, 2025). "Another longitudinal study observed significant improvement in depression and anxiety scores in patients undergoing immunomodulatory and/or TNF-alpha therapy." (PMID 39860505, 2025). "IL-1, IL-6, and TNF-α, on the other hand, lead to neural progression and depression through their pathways." (PMID 40530060, 2025). "Vagus nerve stimulation (VNS): Clinical trials have shown that VNS reduces depressive symptoms in treatment-resistant depression while modulating systemic inflammation, with documented reductions in TNF-α and IL-6 levels." (PMID 40218134, 2025). "The pro‐inflammatory factors such as TNF‐α, IL‐1β, and IL‐6 are classical markers of inflammation frequently studied in the context of depression." (PMID 40491976, 2025). "Inflammatory cytokines, such as TNF-α and IL-6, are elevated in both inflammation and depression, creating a vicious cycle that exacerbates both physical and mental health." (PMID 40115342, 2025). "Concurrently, inflammatory cytokines involved in the pathophysiology of depression, such as IL-6 and TNF-α, directly affect bone metabolism by stimulating osteoclast activity and inhibiting osteoblast function, thereby disrupting bone homeostasis." (PMID 40718425, 2025). "It has been shown that when microglia are activated, they release oxidative products and pro-inflammatory mediators such as TNF-α and IL-1β, which facilitate neuronal damage and contribute to depression." (PMID 40860146, 2025). "Poor sleep symptoms, such as fatigue, cognitive impairment, depression, and sleepiness, are induced by exogenous IL-1 and TNF-α, and their inhibitors (IL-1 receptor antagonist and TNF-α soluble receptor) help alleviate these symptoms in people with insomnia." (PMID 40137863, 2025). "In mice models exposed to chronic unpredictable stress, an increased expression of cytokines IL-1β, IL-6, and TNF-α in the amygdala was observed and mice presented symptoms of depression and anxiety disorder." (PMID 40141110, 2025). "In a recently published meta-analysis on case-control studies of inflammatory cytokines and depression, participants with depressive disorders had a trend toward significantly higher TNF-α." (PMID 39902492, 2025). "Meta-analytic evidence indicates elevated levels of IL-6, CRP, and TNF-α in individuals with depression." (PMID 41333345, 2025). "Escitalopram can reduce the levels of pro-inflammatory cytokines—IL-1β, IL-1ra, IL-2, IL-4, IL-6, IL-8, IFN-y, TNF-α in the serum of patients suffering from depression, while simultaneously increasing the level of anti-inflammatory IL-10." (PMID 41302150, 2025). "One previous study reported that expression of IL-1β was increased as well as IL-6 and TNF-α in PFC of the teenage suicide depression patients, consistent with peripheral findings." (PMID 40179065, 2025). "Future research with larger, independent cohorts and longitudinal follow-up is warranted to validate these findings and further explore the mechanistic role of TNF-α in depression-related cognitive dysfunction." (PMID 41392773, 2025).
depression (continued). "Multiple studies have demonstrated that individuals with depression exhibit elevated proinflammatory cytokines, such as interleukin-6 (IL-6), tumor necrosis factor-α (TNF-α), and C-reactive protein (CRP), and decreased anti-inflammatory mediators." (PMID 41541965, 2025). "Future research endeavors will focus on integrating bone turnover markers, inflammatory factors (e.g., IL-6, TNF-α), and genetic data to elucidate the biological pathways linking depression, osteoporosis, and mortality." (PMID 40988243, 2025). "The norepinephrine transporter is involved in hypertension and depression by regulating TNF-α and IL-6." (PMID 40230380, 2025). "Tianeptine significantly reduced bacterial LPS-induced expression of the pro-inflammatory cytokine TNF-α, while increasing anti-inflammatory cytokine levels, thereby attenuating the severity of periodontitis and improving depression-related behaviors." (PMID 40655932, 2025). "Certain biomarkers elevated in inflammatory and chronic disease states are also found to be increased in depression.Interleukin-6 (IL-6), tumor necrosis factor-α (TNF-α), and cortisol have been linked to depression and are associated with symptom severity." (PMID 40098072, 2025). "qPCR results showed that knockdown of Homer1 improved the expression of inflammation‐related markers IL‐1β, TNF‐α, IL‐10, and depression‐related markers ERCCL2, SLC6A4, and GAD1 in primary neurons, both in the PTSD group and in the TBI+Hcort group." (PMID 39665190, 2025). "The occurrence of neuroinflammation in the depressive state is further confirmed by the higher TNF-α levels in the depression control group." (PMID 40574754, 2025). "Prospective cohorts have reported that higher circulating IL-6 and TNF-α predict subsequent depressive symptoms, consistent with an inflammation-driven subtype of depression." (PMID 41155365, 2025). "Few studies have examined the influence of IBD therapies, mainly TNF inhibitors, on depression and anxiety." (PMID 40807142, 2025). "Depression, anxiety, fatigue, IL-6, and tumor necrosis factor-α had higher strength centrality indices and were identified as the most central nodes within the symptom-biomarker networks." (PMID 40633921, 2025). "Using data from a prospective cohort of Korean patients with depressive disorders undergoing stepwise antidepressant treatment, we aimed to examine the effects of baseline serum TNF-α (sTNF-α) levels on 12-week antidepressant treatment outcomes." (PMID 40955462, 2025). "In MDD group, the age of first onset of depression in females was significantly younger than that in males (p < 0.05), and female serum TNF-α levels were significantly higher than those in males (p < 0.05)." (PMID 39980978, 2025). "Patients with anxiety and depressive disorders have increased levels of pro-inflammatory cytokines (e.g., TNFα, IL-1α, IL-1β, IL-4, IL-5, IL-6, IL-12, and interferon [IFN]-γ) and C-reactive." (PMID 39803412, 2025). "Research conducted on patients suffering from depression disorders indicate in serum the consistently increased levels of pro-inflammatory cytokines such as TNF-α and IL-6, with their combined activity leading to systemic inflammation." (PMID 40722844, 2025). "In our study, XCHT was proven to alleviate depressive disorders by downregulation of IL‐1β, TNF‐α, and IL‐6 inflammasome, modulating the immune system by inhibiting Iba‐1 and GFAP overexpression, making it a promising candidate for the treatment of depression." (PMID 39981856, 2025). "In conclusion, in this pilot study, we have shown that supplementation with LM pectin results in significant drops in TNF-α at 20 g and 15 g per day and in significant drops in anxiety and depression scores at 10 g, 15 g and 20 g per day in healthy humans." (PMID 39408292, 2024).
depression (continued). "In relation to depression, it has been established that TNFα, as do IL-1 and IL-6, induces not only symptoms of physical sickness but also major depressive disorders in physically ill patients with no previous history of mental disorders." (PMID 39358787, 2024). "Brains of AD cases with comorbid depression, compared with AD alone, had increased IL-4 in the superior frontal gyrus and increased TNFα & IL-12p70 in the insula." (PMID 39526037, 2024). "Increasing the pro-inflammatory cytokines, such as TNF-α and NF-κB, is a crucial manifestation of depression." (PMID 39200564, 2024). "Concerning psychosis, TNF-α levels and TNF-β polymorphisms have also been documented and constitute the low-grade inflammation observed in SZ, BD, and major depressive disorders." (PMID 38485715, 2024). "Evidence indicates that injecting TNF-α into the hippocampus can lead to depressive-like behaviors, while IL-1β also promotes depression onset, highlighting the role of central inflammatory factors in depression." (PMID 39595861, 2024). "Lupeol significantly reduces TNF-α production from lipopolysaccharide-stimulated macrophages, thereby reducing anxiety and depression." (PMID 39605919, 2024). "Studies have shown that TNF-α increases ROS levels in microglia, and mitochondrial dysfunction in depression leads to elevated ROS." (PMID 38255289, 2024). "The study explored the correlation between pro-inflammatory cytokines such as TNFα, IL-1β and IL-6 with hippocampal volume and scores on the Beck Depression Inventory." (PMID 38377025, 2024). "Transplantation of OP-modulated microbiota into CUMS receptor mice alleviated depression and anxiety, reduced elevated cytokine levels (TNF-α, IL-1β, IL-6, etc.), and restored histopathological damage in the colon." (PMID 38983862, 2024). "Increases in serum and CSF TNF-α levels have been one of the most consistent findings in AD and depression pathologies." (PMID 39526037, 2024). "There is a great deal of correlational evidence that patients who suffer from anxiety and depression show elevations in circulating levels of cytokines that are pro-inflammatory in nature, such as Tumor necrosis factor alpha, IL-1β, IL-6, and IL-17." (PMID 38255692, 2024). "Pro-inflammatory cytokine levels, such as IL-6 and tumor necrosis factor α (TNF-α), are elevated in the serum and cerebrospinal fluid of patients with depression." (PMID 39484160, 2024). "In animal models of depression, increased levels of pro-inflammatory cytokines, such as IL-1β and TNF-α, and decreased levels of anti-inflammatory cytokines, such as IL-10 and TGF-β1, have been observed in the hippocampus and cortex." (PMID 38575920, 2024). "In a specific study, patients experiencing depression exhibited heightened levels of pro-inflammatory cytokines, including interleukin-1β (IL-1β) and tumor necrosis factor-α (TNF-α)." (PMID 38994205, 2024). "Central ghrelin administration not only improved depression symptoms but also lowered tumor necrosis factor α (TNF-α), interleukin 1β (IL-1β), and IL-6 concentrations." (PMID 38544844, 2024). "Injection of rhodomyrtone decreased the expressions of TNFR1 and TNF-α, resulting in significant improvements in mouse depression-like behaviors and reduction of astrocyte activation." (PMID 38710713, 2024). "Numerous studies have shown that inflammatory mediators and cytokines such as interleukin-1β (IL-1β), interleukin-6 (IL-6), and tumor necrosis factor-α (TNF-α) are frequently present in the peripheral blood of patients with depression." (PMID 39114351, 2024). "In depression research, the inflammatory cytokines IL-6 and TNF-α have been strongly correlated with the pathology and severity of major depression, and the role of oxidative stress in the progression of depression has long been appreciated." (PMID 39158617, 2024).
depression (continued). "TNF-alpha levels were significantly lower in the suicide attempt group (4.18 ± 2.30, than in the depression group (5.33 ± 2.06) and control group 4.72 ± 2.25 (p < 0.001)." (PMID 38737407, 2024). "Specifically IL-4 was increased in the AD + depression group in the superior frontal gyrus and that IL-12p70 and TNFα were increased in the anterior insula." (PMID 39526037, 2024). "FMT from patients with RA into the ABX-treated mice resulted in depression-like behavior, changed gut microbiota composition, elevated levels of IL-6 and TNF-α, and downregulated levels of synaptic proteins in the PFC." (PMID 38983862, 2024). "Depression with high levels of TNF-α stimulates NF-κB, then elevates histone deacetylase 1 activity and represses claudin-5 expression, resulting in loss of tight-junction proteins and disruption of blood-brain barrier." (PMID 38459460, 2024). "Our results are consistent with previous clinical studies, which showed that IL-1β, IL-6, and TNF-α levels were increased in patients with depression." (PMID 39498265, 2024). "Insomnia (sleeplessness) is a potential symptom of stress-induced depression/anxiety (DA), which induces TNF-α expression." (PMID 39519543, 2024). "Numerous studies demonstrated alterations in IL-6 and TNF-α levels in patients with depression, bipolar disorder, schizophrenia, and other psychiatric illnesses." (PMID 38339101, 2024). "Pro-inflammatory factors such as interleukin-1β (IL-1β), interleukin-6 (IL-6), and tumor necrosis factor-alpha (TNF-α) are regarded as depression biomarkers." (PMID 38389919, 2024). "Polymorphisms in genes such as IL-1β, IL-6, IL-10, TNF, MCP1/CCL2, CRP, and phospholipase A2 are among the most consistently observed findings in major depressive disorder." (PMID 39723161, 2024). "Clinical studies have demonstrated that C-reactive protein and TNF-α are positively correlated with self-rating depression scale scores, while BDNF levels are negatively correlated with these scores in women with perimenopausal syndrome." (PMID 38255289, 2024). "Our team’s previous research demonstrated that injection of TNF-α into the hippocampus evoked depression-like behaviors." (PMID 38627830, 2024). "Previous research has suggested that MTZ treatment for major depressive disorders has anti-inflammatory effects and decreases tumor necrosis factor (TNF)-α levels." (PMID 37943296, 2024). "The M1 phenotype leads to a chronic neuroinflammatory reaction, induces the release of proinflammatory cytokines such as TNF-α and IL-1β, exacerbates tissue damage, and further aggravates the pathological process of depression." (PMID 38337722, 2024). "It is important to remember that the “cytokine theory of depression” proposes that enhanced production of proinflammatory cytokines (such as IL-6, IL-1β, IFN-γ, and TNFα) is associated with the pathogenesis of depression." (PMID 38731995, 2024). "The TNF-α levels were highest (P < .001) in the patients with bipolar disorder, followed by those with major depressive disorder and the control group." (PMID 39283831, 2024). "Negative social interactions may increase the levels of pro-inflammatory cytokines, such as IL-6, TNF-α, and positive social support can activate opioid system and produce beta-endorphin that has anti-inflammatory properties, which are associated with depression severity and suicide." (PMID 38459460, 2024). "Serum levels of proinflammatory cytokines such as IL-1, IL-6, and tumor necrosis factor alpha are elevated not only in the patients with depression but also in COPD patients." (PMID 38386662, 2024). "Activation of GPR55 using O-1602 inhibited the activation of the inflammasome, normalizing the increased expression of IL-1β (IL-6 and TNF) and the decreased expression of IL-4 and IL-10, respectively reducing the depression- and anxiety-like behavior." (PMID 38796643, 2024).
depression (continued). "This also explains the increase in 5-HT content, decrease in pro-inflammatory factors TNF-α and IL-6 content, and increase in anti-inflammatory factor IL-10 content in the serum of mice with depression-like behavior after oral administration of asiaticoside." (PMID 39494347, 2024). "Patients with severe depression and animal models of depression often exhibit elevated levels of pro-inflammatory cytokines such as IL-1β, IL-6, and TNF-α." (PMID 38628641, 2024). "Reports show that the concentrations of inflammatory mediators, including IL-6, IL-1β, and TNFα, are elevated in major depressive disorder (MDD)." (PMID 39408923, 2024). "The predictive value of the cytokines IL-1α, IL-6, and TNF-α in the discrimination of patients with severe depression was assessed based on the AUC values, which is also presented graphically by the ROC curve." (PMID 39595067, 2024). "US-exposed mice treated with vehicle exhibited decreased sucrose preference, a sign of anhedonia, a key feature of depression, increased anxiety-like behavior, elevated corticosterone levels, and enhanced TNF and IL-1β gene expression in the brain." (PMID 38912378, 2024). "Elevated mRNA and protein levels of interleukin-1β (IL-1β), IL-6, and TNF-α have also been observed in the PFC of patients with depression who died by suicide." (PMID 39484160, 2024). "Research indicates that individuals with depression exhibit heightened levels of C‐reactive protein, pro‐inflammatory cytokines such as interleukin (IL)‐1, IL‐6, and tumor necrosis factor‐alpha (TNF‐α), along with chemokines." (PMID 39236111, 2024). "In particular, six studies assessed biomarkers at some time during pregnancy in relation to depression during postpartum, showing a potential predictive role of TNF-a and IL-6 in the diagnosis of PPD." (PMID 38820411, 2024). "In some studies, cytokine inhibitor therapies, such as anti-IL-6 biologics, TNF-α inhibitors, IL-12 and IL-23 antagonists were efficacious in depression." (PMID 38459460, 2024). "For instance, a study on adolescent patients with the first-episode of depression highlighted a correlation between pro-inflammatory TNF- and IL-6 signaling and increased anti-inflammatory activity mediated by IL-10 and IL-4." (PMID 38912378, 2024). "Previous studies have shown that the levels of inflammatory markers such as IL-1, IL-6, and TNF-α are significantly elevated in HD patients with depression, suggesting that inflammation plays an important role in the pathogenesis of depression." (PMID 39338552, 2024). "Chronic low-grade inflammation, characterized by the secretion of pro-inflammatory cytokines such as TNF-α and IL-6, is a central link between obesity and depression, establishing a vicious cycle where each condition can exacerbate the other." (PMID 39335507, 2024). "Specifically, greater levels of proinflammatory cytokines (i.e., tumor necrosis factor- (TNF-) and interleukin-18 (IL-18)) have been shown to relate to the severity of agitated depression." (PMID 39199439, 2024). "There is evidence that patients with depression have elevated levels of inflammatory cytokines such as tumor necrosis factor alpha (TNF-α), interleukin 1β (IL-1β), and interleukin 6 (IL-6)." (PMID 38983910, 2024). "Evidence for the association between increased levels of the cytokine TNF-α and IDO has been found in rodent studies of stress-induced depression, where stress caused the upregulation of IDO in the cortex." (PMID 39064698, 2024). "Meanwhile, some inflammatory cytokines secreted by the musculoskeletal system are closely related to the occurrence of depression, such as IL-6, TNF-a, and 5-HT." (PMID 39161853, 2024). "In particular, a significant reduction in depression and anxiety scores was observed after the second and third infusions of infliximab, an anti-TNF treatment." (PMID 38571822, 2024).